PTN (pleiotrophin)
Diseases named in the same sentence as PTN in open-access papers (continued):
Sharing a sentence is not in itself a finding about the gene and the disease.
glioma (continued). "In the present study, the numbers of CREB3L1+ cells in the same microscope’s field of view gradually decreased from the control to the high-grade glioma, whereas the PTN+ cell counts increased in the low- and high-grade glioma tissues as compared with the control." (PMID 29531016, 2018). "Likewise, PTPRZ1 glioma cell/PTN myeloid cell interactions play a key role." (PMID 38712663, 2024). "Moreover, our data suggested that blocking SPP1 and PTN pathways might be a strategy for combating glioma." (PMID 36036011, 2022). "Similarly, compound 1e abolished PTN-induced migration of U87MG glioma cells." (PMID 29651006, 2018). "Furthermore, glioma patients with a higher expression of PTN or ALK have shorter survival times." (PMID 27579614, 2016). "In contrast, glioma afferent signaling mainly involved mode 1 communication patterns, including pathways like VEGF, PTN, and JAM." (PMID 39975552, 2025). "The Glioma C2 subset, characterized by NUSAP expression, was identified as a pivotal player in the PTN signaling cascade." (PMID 39975552, 2025). "EGFR, BCAN, SOX2, PTN and CCN3 were found to be highly elevated in the glioma tumorous tissue with prominent fold change value, while other DE-ARGs, such as CLU, SCG3, showed no distinct expression alteration." (PMID 39033204, 2024). "Tumor-associated macrophages secrete abundant pleiotrophin (PTN) to stimulate glioma stem cells via their receptor PTPRZ1, thereby promoting malignant growth of glioblastoma through PTN-PTPRZ1 paracrine signaling." (PMID 38383423, 2024). "It is known that the protein complex of HSP90B with PTN, SPARC, and SPARCL1 facilitates the migration of glioma cells." (PMID 36033456, 2022). "In the pleiotrophin (PTN)‐PTPRZ1 paracrine signaling, which supports glioma progression, PTN released by TAMs binds to its receptor PTPRZ1 on GSCs, suggesting the significance of TAMs as important components of the CSC niche." (PMID 36226253, 2022). "For example, PTPRZ1/PTN represents one of many spatially heterogeneous glioma:myeloid signaling nodes, and PTPRZ1/PTN signaling has been reported to promote glioma stem cell maintenance and glioma growth." (PMID 35140215, 2022). "Protein complex, containing PTN, SPARC, SPARCL1, and HSP90B, facilitates the migration of glioma cells." (PMID 36033456, 2022). "The group of Anna Dimberg has shown that in a murine glioblastoma model, pleiotrophin activates the anaplastic lymphoma kinase 1 (ALK1), which acts as its receptor and leads to VEGF deposition and vascular abnormalities in gliomas." (PMID 33036204, 2020). "Survival time for patients with CREB3L1− and PTN+ gliomas was shorter than patients with CREB3L1+ and PTN− gliomas in the investigated cohorts (both P<0.05)." (PMID 29531016, 2018). "For its parts, in response to a protein complex containing pleiotrophin, secreted by neural precursor from the PVZ, RhoA signaling is activated in glioma cells and induces the migration of glioma cells to the PVZ." (PMID 30333910, 2018). "In a study conducted by Shi and colleagues in 2017, it was reported that GAMs secrete abundant pleiotrophin (PTN), which stimulates glioma stem cells (GSCs) through its receptor PTPRZ1, thereby promoting malignant growth of glioblastoma (GBM) through PTN–PTPRZ1 paracrine signaling." (PMID 38732975, 2024). "PTN disrupts calcium-dependent cell adhesion and initiates the EMT of glioma cells." (PMID 36429098, 2022). "PTN and its target PTPRZ1 also may help promote stemness, signaling, and proliferation of neural progenitors and glioma tumor cells." (PMID 34101353, 2021). "Considering the expression profiles in glioma cell lines compared with normal astrocytes-HEB, and considering the size of these circRNAs, we selected circPTN, which is derived from the pleiotrophin (PTN) gene, for further study." (PMID 31511040, 2019). "Absence of CREB3L1 and presence of PTN in brain glioma cells correlate with survival time of the glioma patients." (PMID 29531016, 2018).
glioma (continued). "Since these changes of the glioma tumors at the gene level were identical with the results observed at their protein levels, it is reasonable to consider that CREB3L1 and PTN serve as biomarkers for helping to identify the nature of the glial cells and evaluating malignant degrees of brain gliomas." (PMID 29531016, 2018). "Absence of CREB3L1 and presence of PTN expression in the tumor cells correlate with a poor prognosis of the glioma patients." (PMID 29531016, 2018). "PTN has previously been suggested to be an oncogene and is highly expressed in glioma, but its role in tumor initiation has not been investigated prior to this report." (PMID 27806344, 2016). "By employing the RCAS/tv-a mouse model, we provide evidence that PTN is not sufficient to induce glioma development, but augments PDGFB-induced gliomagenesis by increasing Akt activation in neural progenitor cells." (PMID 27806344, 2016). "In the same line, PTN increases CDK5 activity and interaction with p35, in an RPTPβ/ζ-mediated manner, in rat glioma C6 cells that do not express ανβ32,4." (PMID 29651006, 2018).
glioblastoma (41 papers, 2010 to 2025). The most malignant astrocytic tumor (WHO grade IV). "The tumor microenvironment is highly enriched for immunosuppressed M2-like tumor-associated macrophages and glioblastoma stem cells, which promote glioblastoma malignancy through the PTN-PTPRZ1 signaling axis." (PMID 38383423, 2024). "PTN has been implicated in the tumorigenesis of numerous human malignancies, including colorectal cancer, glioblastoma, melanoma, pancreatic cancer, breast cancer and lung cancer." (PMID 28969035, 2017). "Through analysis of publically available datasets, we demonstrate that increased PTN mRNA expression is associated with amplification of chromosome 7, identified as one of the earliest steps in glioblastoma development." (PMID 27806344, 2016). "PTN has also been implicated in a number of tumors including glioblastoma and breast cancer, and its overexpression has been reported to cause malignant transformation in several cell lines." (PMID 22848377, 2012). "Also, in glioblastoma cells PTN has been shown to cause a dephosphorylation of PTPRZ1, which is normally constituently active, resulting in an increase in phosphorylated β-catenin." (PMID 35250852, 2022). "RNA expression profiling of normal and tumor tissues has shown PTN to be consistently expressed in glioblastoma; however, several studies have indicated PTN is elevated in other cancers such as breast, lung, and pancreatic cancer." (PMID 36828390, 2023). "The full length PTN-18 peptide was shown to enhance cell migration whilst a shorter form of PTN, PTN-15 activated mitogenesis in glioblastoma cells." (PMID 35250852, 2022). "The expression levels of circ_COL1A2, circ_PTN, circ_VCAN, circ_PLOD2, circ_SMO, circ_CLIP2, circ_GLIS3, and circ_EPHB4 in glioblastoma (GBM) are significantly higher than those in normal tissues." (PMID 30064463, 2018). "To investigate the expression pattern of PTN in glioblastomas, we employed the Oncomine database which provides a systematic approach to analyze gene expression in publically available microarray datasets." (PMID 27806344, 2016). "Differential analysis of gene expression of five independent datasets confirmed a consistent up-regulation of PTN mRNA in glioblastoma samples as compared with normal white matter." (PMID 27806344, 2016). "We have recently shown that PTN expression is associated with increased vascular abnormality and higher vascular area in the GL261 syngeneic orthotopic model of glioblastoma." (PMID 27806344, 2016). "We used the human U87MG glioblastoma cells that express PTN with human umbilical vein endothelial cells (HUVEC) that express ALK." (PMID 23267434, 2012). "Different laboratories have demonstrated the significance of PTN as a growth and survival factor for different solid tumors including melanoma, pancreatic cancer, glioblastoma, and multiple myeloma to name a few." (PMID 23267434, 2012). "Under pathological conditions, PTN promotes the growth of various tumor cells including glioblastomas, and serves as angiogenic and metastasis promoting factor." (PMID 27721338, 2011). "In previous studies, it has been shown that PTN is highly expressed in tumor cell lines of different origin and that knockdown of PTN results in reduced growth of glioblastoma xenografts." (PMID 27721338, 2011). "In U373-MG glioblastoma cells, the binding of PTN with RPTPβ/ζ inactivates the receptor, and thus significantly increases the tyrosine phosphorylation of β-catenin." (PMID 20565841, 2010). "Further investigations showed that the reduction of PTN mRNA and protein levels results in decreased migration and colony formation in both glioblastoma cell lines." (PMID 20714308, 2010). "Additionally, pleiotrophin (PTN) secreted by CD163+ MDMs binds to protein tyrosine phosphatase receptor type Z1 (PTPRZ1) on the surface of glioblastoma stem cells (GSCs)." (PMID 40800581, 2025).
glioblastoma (continued). "The present study shows that hypoxia or chemical hypoxia increases the PTN expression in endothelial and glioblastoma cells that express ανβ3 integrin in a HIF- and AP-1-dependent manner to negatively impact the stimulatory effect of hypoxia on endothelial cell proliferation and migration." (PMID 40361445, 2025). "In addition, a previous study revealed that tumor-associated macrophages secrete PTN, which is tumor-promoting and positively associated with PTPRZ1 expression and stemness of glioblastoma cells." (PMID 39893177, 2025). "Pleiotrophin secretion by TAM promotes signaling in glioblastoma stem cells and tumor growth." (PMID 39075190, 2024). "Previous research data has indicated that blocking the PTN pathway may serve as a means to combat glioblastoma." (PMID 39403379, 2024). "Consequently, RNA expression profiling of normal and tumor tissues in the CNS shows PTN to be consistently expressed at higher levels in glioblastoma." (PMID 36828390, 2023). "Large amounts of TAMs secrete pleiotrophin (PTN) protein in glioblastoma tumors." (PMID 36568388, 2022). "Additionally, TAMs are also known to secrete pleiotrophin (PTN) that promotes glioblastoma tumor growth and stem cell maintenance via protein tyrosine phosphatase receptor type Z1 (PTPRZ1) signaling." (PMID 34503065, 2021). "Overall, only the most aggressive, high grade tumors, i.e., GBM (glioblastoma multiforme) and anaplastic oligodendroglioma showed an increased expression of PTN and ALK mRNA relative to normal brain tissues, relative to adjacent brain tissues and relative to low grade tumors (p < 0.01)." (PMID 23267434, 2012). "In accordance with previous studies, we could also show that the expression of the tumor-relevant growth factor PTN is rate-limiting for the growth of glioblastoma xenografts." (PMID 27721338, 2011). "In addition, PTPRZ1 and its ligand pleiotrophin are overexpressed in human glioblastoma and there is substantial evidence that these proteins play an important role in the pathogenesis of this cancer." (PMID 20224786, 2010). "Scientists have tested the hypothesis that the growth of human glioblastomas can be controlled by regulating PTN expression." (PMID 20714308, 2010). "However, PTN is overexpressed in a number of cancers, such as human breast cancer, melanocytic tumors, and glioblastoma." (PMID 20565841, 2010). "Therefore, we hypothesized that the C0 subgroup was essential in the PTN pathway and impacted the advancement of glioblastoma via this pathway." (PMID 39403379, 2024). "PTN may also act as a ligand of ALK to maintain the cancer stem cell phenotype of glioblastoma." (PMID 28969035, 2017). "Eight circRNAs, including circ_COL1A2, circ_PTN, circ_VCAN, circ_SMO, circ_PLOD2, circ_GLIS3, circ_EPHB4, and circ_CLIP2 showed significantly higher expression in glioblastoma (GBM) than in normal tissues." (PMID 28969099, 2017). "Consistently, both astrocytes and meningioma cells in coculture samples increased expression of the PTPRZ1 ligand PTN over time, which activates PTPRZ1 to promote glioblastoma stem cell renewal and tumor growth." (PMID 32968068, 2020). "In addition, neural-precursor cells can secrete factors such as PTN and ROCK that were shown to drive glioblastoma invasion to the SVZ." (PMID 34359668, 2021). "Further studies show that PTN could induce the activation of the PI3K/AKT-related pathway in bovine epithelial lens cells, glioblastoma cells, NIH3T3 fibroblasts, and human umbilical vein endothelial cells." (PMID 28678802, 2017). "In addition, there are two types of PTNs: immobilized pleiotrophin (PTN18), which promotes migration via the cell surface receptor, the protein tyrosine phosphatase receptor zeta (PTPRZ1), and soluble pleiotrophin (PTN15), which is mainly involved in promoting glioblastoma proliferation." (PMID 35204054, 2022).
glioblastoma (continued). "Interestingly, two naturally occurring forms of PTN (18 and 15 kDa) that differ by 12 amino acids at their C-terminal region, differentially promote glioblastoma migration and proliferation." (PMID 30427932, 2018). "The finding that PTN is elevated in PTC suggests that PTN overexpression may promote growth of PTCs, which has also been suggested for other cancers, such as ovarian, pancreatic, glioblastoma, prostate cancer and breast cancer." (PMID 26914549, 2016).
breast carcinoma (22 papers, 2002 to 2026). "We found that pleiotrophin (PTN), a neurotrophic cytokine, is a metastasis-associated factor that is expressed highly by aggressive breast cancers." (PMID 36828390, 2023). "Instead, we report for the first time, PTN to be a “metastasis-associated factor” in mouse and human breast cancer." (PMID 36828390, 2023). "To further test if PTN expression is associated with metastatic cancer cells, we looked at PTN expression in cells derived from the mouse genetic breast cancer model, MMTV-PyMT." (PMID 36828390, 2023). "Circulating PTN levels in humans have been associated with advancing age, and changes have been proposed as a potential diagnostic and prognostic tool for diseases like breast cancer, multiple sclerosis, and multiple myeloma disease status." (PMID 41303424, 2025). "We found that PTN expression is associated with advanced disease in breast cancer patients and that elevated expression of PTN might be an independent predictor of metastasis." (PMID 36828390, 2023). "High PTN/PTPRZ1 expression is associated with poor chemosensitivity in breast cancer patients." (PMID 30497491, 2018). "By contrast, serum PTN protein levels have been shown by multiple studies to be elevated in breast cancer patients relative to healthy controls." (PMID 42193935, 2026). "Highly expressed PTN strikingly increased the synthesis of collagen and elastin in breast cancer derived from MMTV-PyMT transgenic mice, but the detailed mechanism was unclear." (PMID 40069574, 2025). "Previous studies in breast cancer highlighted that PTPRZ1 was a risk factor for poor prognosis in TNBC and found that PTN-PTPRZ1 was driven by chemotherapy, indicating its role in chemoresistance that gives rise to disease recurrence." (PMID 39518121, 2024). "Previous studies in breast cancer highlighted that PTPRZ1 is a risk factor for poor prognosis in TNBC and found that PTN-PTPRZ1 is driven by chemotherapy, indicating its role in chemoresistance." (PMID 39518121, 2024). "Accordingly, determination of PTN levels has been proposed as a potential tool for the diagnosis and prognosis of breast cancer." (PMID 37484951, 2023). "When studied in the context of breast cancer, PTN has been reported to be a cancer cell–derived factor only." (PMID 36828390, 2023). "Further, when we compared PTN expression by immunohistochemistry (IHC) in 19 paired tumor and lymph node metastasis samples from human breast cancer patients, we observed higher PTN protein expression in cancer cells in lymph node metastases." (PMID 36828390, 2023). "To address this, we accessed single-cell RNA sequencing data (scRNAseq) from human breast cancer and found that PTN was expressed by a population of tumor cells and lowly by multiple stromal components, including endothelial cells." (PMID 36828390, 2023). "Overall, our results provide an in vivo functional analysis of PTN in breast cancer progression and demonstrate that inhibition of this previously understudied protein has significant therapeutic potential for the treatment of metastatic breast cancer." (PMID 36828390, 2023). "Aligned with this notion, we report that PTN is essential in forming robust metastasis as blocking it reduces metastatic outgrowth in multiple mouse models of breast cancer." (PMID 36828390, 2023). "Overall, our results, for the first time, present a comprehensive in vivo functional analysis of PTN in breast cancer." (PMID 36828390, 2023). "The phenotype of reduction in metastasis after PTN blockade held true in the MMTV-PyMT spontaneous breast cancer model as well." (PMID 36828390, 2023). "PTN expression in other cancers, specifically breast cancer, has provided mixed results, with data from TCGA showing lower RNA expression of PTN in breast cancer compared with normal tissue." (PMID 36828390, 2023).